ZMYM6 (zinc finger MYM-type containing 6)
Description:
Required for regulation of cell morphology and cytoskeletal organization.
Synonyms: Buster2; KIAA1353; ZNF258; ZNF198L4; MYM; ZBED7
Tractability: PROTAC: ubiquitination databases record sites on it.
Gene: Protein-coding gene on chromosome 1 (34,986,144 to 35,031,951, reverse strand). Ensembl gene ENSG00000163867.
Subcellular location: Nucleus
Subcellular location (Human Protein Atlas): Nucleoplasm
Gene Ontology:
Molecular function: protein binding; DNA binding; zinc ion binding
Cellular component: nucleoplasm; nucleus
Genetic constraint (gnomAD): Loss-of-function variants: 86 observed, 133.13 expected, observed/expected ratio (o/e) 0.65, 90% interval 0.54 to 0.77. The upper end of that interval is the gene's LOEUF score, 0.77, which puts it in group 3 of 6, group 1 being the genes least tolerant of losing a copy. Missense variants: 1,336 observed, 1,587.7 expected, observed/expected ratio (o/e) 0.84, 90% interval 0.8 to 0.88. Synonymous variants: 476 observed, 545.49 expected, observed/expected ratio (o/e) 0.87, 90% interval 0.81 to 0.94.
Homologues: Orthologues: chimpanzee ZMYM6 (99% identical), macaque ZMYM6 (98% identical), pig ZMYM6 (88% identical), dog ZMYM6 (88% identical), guinea pig ZMYM6 (85% identical), rabbit ZMYM6 (82% identical), mouse Zmym6 (67% identical), rat Zmym6 (67% identical). Paralogues in human: ZMYM4 (43% identical), ZMYM2 (23% identical), ZMYM1 (22% identical), ZMYM3 (21% identical), ZMYM5 (9% identical), QRICH1 (8% identical), GTF2IRD1 (7% identical), THAP12 (6% identical), KIAA1958 (5% identical), ZBED11 (5% identical), GTF2I (5% identical), ZBED8L (5% identical), and 6 more.
Diseases named in the same sentence as ZMYM6 in open-access papers:
ZMYM6 is named in the same sentence as 7 diseases in open-access papers, as found by Europe PMC text mining. Sharing a sentence is not in itself a finding about the gene and the disease. The quoted sentences say what the papers report.
mental disorder (1 paper, 2020). A disease that has its basis in the disruption of mental process. "In addition, Ephx1 and several other genes (Pla2r1, Zmym6, Trappc9, and Nqo2) are annotated in the RGD as genes associated with neurodegenerative diseases and/or mental disorders." (PMID 32429546, 2020).
ZMYM6 also shares sentences with these, for which no sentence is quoted: tumor (2 papers); breast carcinoma (1); cancer (1); cervical cancer (1); mental retardation (1); neurodegenerative disease (1).